SCYL3 (SCY1 like pseudokinase 3)
Description:
May play a role in regulating cell adhesion/migration complexes in migrating cells.
Synonyms: PACE1; PACE-1
Tractability: PROTAC: ubiquitination databases record sites on it.
Gene: Protein-coding gene on chromosome 1 (169,846,981 to 169,894,267, reverse strand). Ensembl gene ENSG00000000457.
Subcellular location: Cytoplasm; Golgi apparatus; Cell projection, lamellipodium
Subcellular location (Human Protein Atlas): Cytosol; Golgi apparatus
Gene Ontology:
Molecular function: kinase activity; protein binding; ATP binding
Biological process: cell migration
Cellular component: cytoplasm; cytosol; Golgi apparatus; lamellipodium
Genetic constraint (gnomAD): Loss-of-function variants: 28 observed, 57.66 expected, observed/expected ratio (o/e) 0.49, 90% interval 0.36 to 0.67. The upper end of that interval is the gene's LOEUF score, 0.67, which puts it in group 2 of 6, group 1 being the genes least tolerant of losing a copy. Missense variants: 627 observed, 734.3 expected, observed/expected ratio (o/e) 0.85, 90% interval 0.8 to 0.91. Synonymous variants: 243 observed, 275.81 expected, observed/expected ratio (o/e) 0.88, 90% interval 0.79 to 0.98.
Homologues: Orthologues: chimpanzee SCYL3 (99% identical), macaque SCYL3 (95% identical), pig SCYL3 (88% identical), rabbit SCYL3 (88% identical), dog SCYL3 (87% identical), guinea pig SCYL3 (84% identical), mouse Scyl3 (83% identical), rat Scyl3 (81% identical), zebrafish scyl3 (55% identical), tropical clawed frog scyl3 (55% identical), Drosophila melanogaster CG1344 (27% identical). Paralogues in human: SCYL1 (22% identical), SCYL2 (18% identical).
Diseases named in the same sentence as SCYL3 in open-access papers:
SCYL3 is named in the same sentence as 7 diseases in open-access papers, as found by Europe PMC text mining. Sharing a sentence is not in itself a finding about the gene and the disease. The quoted sentences say what the papers report.
breast carcinoma (1 paper, 2020). "ADCK5, ETNK2, PSKH2, RPS6KC1, and SCYL3 are all significantly focally amplified in breast cancer samples as well but are not located in a peak region." (PMID 33205077, 2020).
cancer (3 papers, 2020 to 2022). A tumor composed of atypical neoplastic, often pleomorphic cells that invade other tissues. "Cox-proportional hazard ratios on Tdark kinases and their CNAs reveal that SBK2, ETNK2, PSKH2, SCYL3, and NRBP2 are all significantly prognostic for survival across all cancers." (PMID 33205077, 2020).
tumour (1 paper, 2025). "Nineteen genes (44%) demonstrated loss or promoter silencing of the wildtype allele in at least one tumour, with six genes (SLC12A4, LOXL2, ZCCHC4, LLGL2, MIPOL1, SCYL3) demonstrating this in multiple samples." (PMID 39794353, 2025). "Eight genes (CDH23, HARS2, LLGL2, LTBP1, MAP6D1, MIPOL1, SCYL3, ZNF418) showed some degree of promoter methylation in at least one tumour, but only MIPOL1 exhibited probable homozygous methylation in more than one sample." (PMID 39794353, 2025).
SCYL3 also shares sentences with these, for which no sentence is quoted: amyotrophic lateral sclerosis (1 paper); neurodegenerative disease (1); type 2 diabetes mellitus (1); venous thromboembolism (1).